CTSK (cathepsin K)
Diseases named in the same sentence as CTSK in open-access papers (continued):
Sharing a sentence is not in itself a finding about the gene and the disease.
lymph node metastasis (5 papers, 2013 to 2025). "This suggests that CTSK is closely associated with the progression of GC, especially early lymph node metastasis and prognosis." (PMID 37930479, 2023). "In HNC, particularly oral squamous cell carcinoma, CTSK is overexpressed in tumor and stromal cells, correlating with lymph node metastasis and poor prognosis." (PMID 40606440, 2025). "In total, 121 mobile tongue OTSCCs and 10 lymph node metastases were analyzed for cathepsin K expression." (PMID 23951042, 2013). "The involvement of Cathepsin K in PD may contribute to more destructive forms of OSCC, since upregulation of Cathepsin K was shown to be linked with lymph node metastasis and unfavorable prognosis in OSCC." (PMID 35047982, 2020). "Another CTSK expression upregulation is GC in which coronin 3 promotes metastasis through upregulation of MMP-9 and CTSK expression and shows a strong link with GC lymph node metastasis and unfavorable prognosis." (PMID 37930479, 2023).
renal carcinoma (5 papers, 2020 to 2023). A carcinoma arising from the epithelium of the renal parenchyma or the renal pelvis. "In an ErK rat model of experimental TSC2 gene mutation, CTSK was used as a detection marker for renal cancer cells." (PMID 36005209, 2022). "According to the latest research, selective inhibition of CTSK by ODN can increase the production of reactive oxygen species (ROS) in mitochondria of human renal carcinoma Caki cells, promote mitochondrial fusion and finally enhance tumour cell apoptosis." (PMID 34053135, 2021). "Given the established role of mTOR inhibitors as a pharmacological option in renal cancers, cathepsin K could be of use as a predictive marker of therapy response and as a potential target." (PMID 34069976, 2021). "Recently, it was reported that selective inhibition of CTSK by ODN could increase the production of ROS in mitochondria of human renal carcinoma Caki cells." (PMID 34053135, 2021).
squamous cell carcinoma (5 papers, 2013 to 2024). A carcinoma arising from squamous epithelial cells. "In squamous cell carcinoma, mesenchymal fibroblasts expressing Cathepsin K are secreted by tumor cells through interleukin-1 stimulation and are associated with tumor aggressiveness." (PMID 32927648, 2020). "CTSK was expressed in non-small cell lung cancer (NSCLC) as adenocarcinoma, adenosquamous carcinoma, squamous cell carcinoma (SCC), and large cell carcinoma, but rarely studied in small cell lung carcinoma (SCLC)." (PMID 37198626, 2023). "By contrast, the majority of squamous cell carcinomas of the skin exhibited no positive immunoreactivity for cathepsin K in the tumor cells (only 2/38 cases were weakly positive), while the peritumoral stromal cells were markedly positive for cathepsin K." (PMID 23833636, 2013).
glioblastoma (4 papers, 2014 to 2024). The most malignant astrocytic tumor (WHO grade IV). "There is one study that shows CXCR4‐induced invasion in a 3D setting, increased invasion of glioblastoma spheroids which could be abrogated through proteolytic cleavage of CXCL12 by cathepsin K." (PMID 29959873, 2018). "Cathepsin K (CTSK), a cysteine protease, plays a significant role in tissue invasion and angiogenesis within glioblastoma multiforme (GBM)." (PMID 38214842, 2024).
heart failure (4 papers, 2015 to 2024). Inability of the heart to pump blood at an adequate rate to meet tissue metabolic requirements. "Elevated levels of Cathepsin K have been demonstrated in both human and animal models of heart failure, atherosclerosis, and coronary heart disease." (PMID 29880809, 2018). "The lysosomal cysteine protease Cathepsin K is elevated in humans and animal models of heart failure." (PMID 29880809, 2018). "CTSK overexpression has also been observed in malignant tumours and heart failure." (PMID 38594611, 2024).
lymphangioleiomyomatosis (4 papers, 2013 to 2026). A multifocal neoplasm with perivascular epithelioid cell differentiation affecting almost exclusively females of child-bearing age. "Recently, cathepsin K overexpression and release was also found in lymphangioleiomyomatosis (LAM), a rare nodule-forming disease." (PMID 30897858, 2019). "However, immunohistochemical stains demonstrated tumor positivity for HMB45, desmin, and Cathepsin K, and genetic testing revealed a TSC1 variant, leading to a definite diagnosis of uterine PEComa with lymphangioleiomyomatosis (LAM)-like features." (PMID 41755808, 2026). "In addition, CTSK is overexpressed in lymphangioleiomyomatosis (LAM) cells and related renal angiolipomas." (PMID 23483898, 2013).
oncocytic neoplasm (4 papers, 2021 to 2024). A usually benign neoplasm composed of large cells with abundant eosinophilic granular cytoplasm. "Nevertheless, cathepsin K is expressed in other oncocytic neoplasms, such as the recently described eosinophilic solid and cystic renal cell carcinoma." (PMID 35980471, 2022).
aneurysm (3 papers, 2013 to 2019). Bulging or ballooning in an area of an artery secondary to arterial wall weakening. "Furthermore, AngII treatment of macrophages stimulated increased production of cathepsin F, which may specifically compensate for cathepsin K in AngII-induced aneurysms compared to the elastase model." (PMID 31546645, 2019). "Additionally, more OLCs from aneurysms express HIF-1α, and produce more MMP-9 and cathepsin K, than myeloid cells from the same tissue." (PMID 31546645, 2019). "However, the AngII-induced aneurysm model, in apoE−/−, cathepsin K−/− double KO mice, showed no attenuation of aneurysm formation." (PMID 31546645, 2019). "Expression of cathepsin K, a strong elastase which is highly expressed in osteoclasts and vital for their function in bone degradation, was of particular interest in our hypothesis of OLC involvement in aneurysm formation." (PMID 31546645, 2019). "The apparent effect on cathepsin K and S but not on MMPs is intriguing and may explain the reported beneficial effect of statin therapy on aneurysm progression as well as the apparent beneficial effects of statins in acute coronary syndromes." (PMID 23349755, 2013).
angiomyolipoma (3 papers, 2017 to 2022). A neoplasm with perivascular epithelioid cell differentiation often associated with tuberous sclerosis. "Based on these observations, it was expected that cathepsin K would be expressed in the angiomyolipoma." (PMID 34069976, 2021). "Of note, the expression of cathepsin K in osteoclasts is regulated by MiTF, a transcription factor expressed in angiomyolipoma, which is significantly reduced by mTOR inhibitors." (PMID 34069976, 2021). "Conversely, epithelioid angiomyolipoma will exhibit at least focal labeling for melanocytic markers, including HMB-45, melan-A, and MiTF, as well as usually diffuse labeling for cathepsin K." (PMID 29090117, 2017). "ESC RCC can express Melan A, HMB45 or Cathepsin K. PAX-8 positivity rules out an epithelioid angiomyolipoma, in addition to absence of other morphological features of AML." (PMID 34514562, 2022).
Anxiety (3 papers, 2011 to 2025). Intense feelings of nervousness, tension, or panic often arise in response to interpersonal stresses. "Cathepsin K deficiency also increases dopamine 2-receptor levels, causing learning impairments and reduced anxiety." (PMID 41325840, 2025). "The analysis of neuronal markers demonstrated that the architecture of the neuronal layers was affected by cathepsin K deficiency in particular in the hippocampus, a region of the CNS known for its importance in the regulation of anxiety and memory." (PMID 21794126, 2011). "In the brain of cathepsin K-deficient animals, the analysis of neuronal markers demonstrated that the architecture of the neuronal layers was affected by cathepsin K deficiency in the hippocampus, a region important in regulation of anxiety and memory." (PMID 34944440, 2021).
clear cell renal cell carcinoma (3 papers, 2021 to 2023). "Cathepsin K, HMB-45, and Melan-A can help in distinguishing renal epithelioid-AMLs from clear cell renal cell carcinomas." (PMID 36740682, 2023).
glaucoma (3 papers, 2014 to 2023). Increased pressure in the eyeball due to obstruction of the outflow of aqueous humor. "In addition, we also explored whether CTSK is regulated by dexamethasone (DEX), TGFβ2, Endothelin 1 (Endo-1), and connective tissue growth factor (CTGF); each of which has been implicated in elevated IOP and glaucoma." (PMID 34831087, 2021).
glioma (3 papers, 2020 to 2023). A benign or malignant brain and spinal cord tumor that arises from glial cells (astrocytes, oligodendrocytes, ependymal cells). "For example, in glioma stem cells, CTSK is responsible for the cleavage and inactivation of stromal-derived factor-1a, and this inactivation promotes stemness loss and increased sensitivity to chemoradiotherapy in glioma stem cells." (PMID 36552871, 2022). "Thus, we performed quantitative real-time PCR (qRT-PCR) analyses, which confirmed that CTSH, CTSO, CTSF, CTSK, CTSS, CTSV and CTSB were significantly downregulated in glioma cells treated with ar-turmerone." (PMID 37768200, 2023). "Moreover, those GSCs express not only a SDF-1/CXCR4 axis but also osteopontin (OPN) and cathepsin K (CTSK), showing how the niche that surrounds arterioles resembles bone marrow hematopoietic stem cell (HSC) niche proteins and recruits glioma stem cells by promotion of migration via CD44 and CXCR4." (PMID 33322379, 2020).
kidney cancer (3 papers, 2022 to 2025). Primary or metastatic malignant neoplasm involving the kidney. "Many studies on kidney cancer recognized that CTSK’s high expression demonstrates the progression of cancer." (PMID 37198626, 2023). "Hence, CTSK plays a key role in the progression of kidney cancers." (PMID 36005209, 2022).
mesenchymal neoplasms (3 papers, 2021 to 2024). "These latter mesenchymal tumors are made up of epithelioid cells, sometimes showing melanin pigment deposition, co-expressing smooth muscle actin, cathepsin K, and melanogenesis markers." (PMID 39410016, 2024). "Increased expression and activity of cathepsin K have been demonstrated in patients, either with mesenchymal tumors or epithelial neoplasms, such as bone cancer, prostate cancer, breast cancer, melanoma, colorectal cancer, and lung cancer." (PMID 34069976, 2021). "Conversely to epithelial neoplasms in which cathepsin K has an important role in the differential diagnosis, in the mesenchymal tumor its immuno-expression is not discriminatory." (PMID 34069976, 2021).
oral lichen planus (3 papers, 2023 to 2024). Oral lichen planus is a chronic inflammatory oral condition of unknown aetiology characterized by T-cell-mediated chronic immune response and abnormal epithelial keratinization cycle. "But whether cathepsin K is involved in the degradation of extracellular collagen and elastin degradation in oral lichen planus remains unclear." (PMID 37334378, 2023). "Interestingly, cathepsin K could coexist with TLR4 and TLR9 in some oral mucosal cells, which reveals that the TLR pathway and cathepsin K may interact in oral lichen planus." (PMID 37334378, 2023).
Osteopenia (3 papers, 2011 to 2020). Osteopenia is a term to define bone density that is not normal but also not as low as osteoporosis. "Targeted deletion of BK channel revealed a juvenile osteopenia in mice accompanied with increased plasma Cathepsin K levels, reduced bone mineral density and increased porosity of trabecular meshworks of long bones and vertebrae, but without obvious fragility fractures." (PMID 21695131, 2011).
Renal Tumors (3 papers, 2021 to 2024). "This review summarizes most of the recent findings of cathepsin K expression, highlighting its role in renal tumors for diagnostic purposes and as a potential molecular target." (PMID 34069976, 2021). "The role of cathepsin K immunoexpression is widened as a diagnostic tool in several renal tumors." (PMID 34069976, 2021). "We present a distinct renal tumor characterized by high-grade eosinophilic cells, cathepsin-K immunohistochemical expression, and harboring mTOR gene mutations demonstrating a malignant potential and showing responsiveness to mTOR inhibitors." (PMID 37938323, 2023). "We found morphological and immunohistochemical features (PAX8, cytokeratin 8–18, cathepsin-K clone 3F9 positivity, and vimentin negativity) overlapping with those observed in the primary renal tumors." (PMID 37938323, 2023). "Although the role of cathepsin K is limited in the physiological processes of the kidney, it has been broadly studied in renal tumors since its first description in translocation renal cell carcinoma in 2009." (PMID 34069976, 2021). "This review describes the usefulness of cathepsin K in the differential diagnosis of renal neoplasms, highlighting the biological knowledge underpinning its expression." (PMID 34069976, 2021). "In this report, we offer a review of cathepsin K, specifically among renal tumors, highlighting its role in the differential diagnosis and as a possible molecular target." (PMID 34069976, 2021). "In the future, uropathologists may implement the use of cathepsin K to establish a diagnosis among renal tumors with clear cells, papillary architecture, and oncocytic features." (PMID 34069976, 2021). "The renal tumors, including the skull and liver metastases, showed immunoexpression PAX8, CK8-18, and cathepsin-K, and negativity for vimentin." (PMID 37938323, 2023).
synovitis (3 papers, 2014 to 2024). Inflammation of a synovial membrane. "Previous paper has indicated that overexpression of cathepsin K gene resulted in progressive synovitis and aggravated destruction of the articular cartilage and the bone." (PMID 25374443, 2014).
translocation renal cell carcinoma (3 papers, 2021 to 2022). "Currently, cathepsin K immunostaining is generally used by uropathologists to reach the proper diagnosis of translocation renal cell carcinoma." (PMID 34069976, 2021). "In the beginning, the idea of the cathepsin K expression in translocation renal cell carcinoma was postulated based on the consistent ability of MiTF to modulate the cathepsin K gene promoter in osteoclasts." (PMID 34069976, 2021). "A previous study showed that CTSK and TFE3 remain the most sensitive and specific biomarkers for Xp11 translocation renal cell carcinoma." (PMID 36005209, 2022).
adenoma (2 papers, 2017 to 2022). A neoplasm arising from the epithelium. "We also found that the higher CTSK expression was associated with higher rate of compression symptoms and large adenomas." (PMID 36052250, 2022).
alveolar soft part sarcoma (2 papers, 2017 to 2021). An alveolar soft part sarcoma occurring in adults. "Interestingly, ASPCSR1-TFE3 gene fusion is also characteristic of alveolar soft part sarcoma, a rare soft tissue sarcoma, which is strongly positive for cathepsin K." (PMID 34069976, 2021).
atrial fibrillation (2 papers, 2020 to 2023). A disorder characterized by an electrocardiographic finding of a supraventricular arrhythmia characterized by the replacement of consistent P waves by rapid oscillations or fibrillatory waves that vary in size, shape and timing and are accompanied by an irregular ventricular response. "Blood CTSK levels were reported to be much higher in patients with persistent atrial fibrillation compared to those of patients with paroxysmal atrial fibrillation." (PMID 37202785, 2023).
autoimmune disease (2 papers, 2024). A disorder resulting from loss of function or tissue destruction of an organ or multiple organs, arising from humoral or cellular immune responses of the individual to their own tissue constituents. "Worth noting is the fact that other members of the cathepsin family, such as cathepsin S and cathepsin K, have received more attention as drug targets for autoimmune diseases." (PMID 38521921, 2024).
bone metastasis (2 papers, 2018 to 2019). Transfer of a neoplasm from its primary site to bones. "LIPUS treatment impaired MDA-MB-231 cell dependentosteoclast differentiation and produced a reduction of osteoclast markers such as Cathepsin K, Matrix Metalloproteinase 9 and Tartrate Resistant Acid Phosphatase, suggesting its role as an effective and safe adjuvant in bone metastasis management." (PMID 30126457, 2018).
chondrosarcoma (2 papers, 2010 to 2024). A malignant cartilaginous matrix-producing mesenchymal neoplasm arising from the bone and soft tissue. "Cathepsin K, for example, is thought to play a role in human chondrosarcoma progression, and it is expressed at highest levels in tibia SRC tumors." (PMID 20809981, 2010). "Cathepsin K immunoexpression is non-specific and has been reported in renal cell tumors, granular cell tumors, as well as numerous additional sarcomas including Kaposi sarcoma, liposarcoma, chondrosarcoma, undifferentiated pleomorphic sarcoma, and leiomyosarcoma." (PMID 37218666, 2024).
colitis (2 papers, 2022 to 2025). Inflammation of the colon. "For instance, cathepsin K (CTSK) from the microbiota can induce TLR4-dependent anti-inflammatory macrophages, and SCFA-producing bacteria collectively suppress JAK/STAT3/FOXO3 signaling to ameliorate colitis." (PMID 41150761, 2025).
coronary artery disease (2 papers, 2022). "Interestingly, most of these pro-inflammatory genes like CCL5, CXCL10, CXCL9, CTSK, and CD14 have been previously reported to be elevated in the serum of patients with coronary artery diseases." (PMID 35488341, 2022).
degenerative disc disease (2 papers, 2011 to 2024). "Another study analysing the bony and soft tissue surgical specimens of patients with AS and degenerative disc disease found elevated cathepsin K and MMP1, which have been implicated in bone resorption and cartilage tissue destruction." (PMID 38405075, 2024). "Although there is not a large body of literature addressing cathepsin K and its role in disc degeneration, there are several previous interesting studies." (PMID 21880134, 2011).
gastric adenocarcinoma (2 papers, 2022 to 2023). "Pancancer analysis suggested that PLAU and CTSK were differentially expressed in pancreatic cancer and other cancers such as kidney chromophobe, stomach adenocarcinoma, and v = ovarian serous cystadenocarcinoma." (PMID 38077303, 2023).
giant cell tumor of bone (2 papers, 2020 to 2022). "The role of CTSK in a giant cell tumor of bone should not be ignored." (PMID 36005209, 2022).
joint disease (2 papers, 2022 to 2024). "Cathepsin K is a cysteine protease that has mostly been studied in the context of bone and joint disorders." (PMID 35501334, 2022).